BICDL1 (BICD family like cargo adaptor 1)
Description:
Acts as an adapter protein linking the dynein motor complex to various cargos and converts dynein from a non-processive to a highly processive motor in the presence of dynactin. Facilitates the interaction between dynein and dynactin and activates dynein processivity (the ability to move along a microtubule for a long distance without falling off the track). Predominantly recruits 2 dyneins, which increases both the force and speed of the microtubule motor. Component of secretory vesicle machinery in developing neurons that acts as a regulator of neurite outgrowth. Regulates the secretory vesicle transport by controlling the accumulation of Rab6-containing secretory vesicles in the pericentrosomal region restricting anterograde secretory transport during the early phase of neuronal differentiation, thereby inhibiting neuritogenesis.
Synonyms: BICDR-1; CCDC64A; BICDR1; CCDC64; FLJ26450; H_267D11.1
Tractability: No criterion of Open Targets' tractability assessment is met for any kind of drug.
Gene: Protein-coding gene on chromosome 12 (119,988,925 to 120,094,496, forward strand). Ensembl gene ENSG00000135127.
Subcellular location: Cytoplasm, cytoskeleton; Cytoplasm, cytoskeleton, microtubule organizing center, centrosome
Subcellular location (Human Protein Atlas): Cytosol; Nucleoplasm; Vesicles
Gene Ontology:
Molecular function: dynactin binding; small GTPase binding
Biological process: Golgi to secretory granule transport; neuron projection development; vesicle transport along microtubule
Cellular component: centrosome; cytoskeleton
Genetic constraint (gnomAD): Loss-of-function variants: 20 observed, 65.49 expected, observed/expected ratio (o/e) 0.31, 90% interval 0.21 to 0.44. The synonymous counts are far from expectation, so gnomAD's model fits this gene poorly and the ratio says little. Missense variants: 691 observed, 730.6 expected, observed/expected ratio (o/e) 0.95, 90% interval 0.89 to 1.01. Synonymous variants: 380 observed, 309.08 expected, observed/expected ratio (o/e) 1.23, 90% interval 1.13 to 1.34.
Homologues: Orthologues: chimpanzee BICDL1 (92% identical), rabbit BICDL1 (89% identical), rat Bicdl1 (89% identical), mouse Bicdl1 (87% identical), guinea pig BICDL1 (87% identical), pig BICDL1 (87% identical), dog BICDL1 (82% identical), macaque BICDL1 (79% identical), tropical clawed frog bicdl1 (66% identical), zebrafish bicdl1 (53% identical), Drosophila melanogaster CG32137 (29% identical). Paralogues in human: BICDL2 (28% identical), SPDL1 (14% identical).
Diseases named in the same sentence as BICDL1 in open-access papers:
BICDL1 is named in the same sentence as 2 diseases in open-access papers, as found by Europe PMC text mining. Sharing a sentence is not in itself a finding about the gene and the disease. The quoted sentences say what the papers report.
chlamydial infection (1 paper, 2022). "Thus, the downregulation of BICDL1 in persistent chlamydial infection suggested the slow development of C. trachomatis in the persistent stage." (PMID 35252346, 2022).
BICDL1 also shares sentences with these, for which no sentence is quoted: infection (1 paper).